TLR3 (toll like receptor 3)
Diseases named in the same sentence as TLR3 in open-access papers (continued):
Sharing a sentence is not in itself a finding about the gene and the disease.
viral infection (continued). "Polyinosinic:polycytidylic acid has been associated with Toll-like receptor-3 (TLR3), a receptor that is specific to dsRNA viral infection, as it activates cytokines (including interleukin-1β, interleukin-6, and tumor necrosis factor-α), causing an inflammatory response." (PMID 35273483, 2022). "It was reported that the TLR3 deficiency may lead to increased incidences of viral infections and impair the production of type I IFN throughout SARS-CoV-2 infection." (PMID 35694544, 2022). "It is usually a negative regulator of TLR3, and IL-1β consequently could reduce the antiviral defence function of the epithelium and cause an increase in viral infections susceptibility." (PMID 35469122, 2022). "Focusing on the second most mapped pathway, human papillomavirus infection, the identified proteins included those that are associated with signaling from toll-like receptor 3 (TLR3) that recognize the dsRNA received from endosomes to interferon beta (INF-β) that suppress viral infection." (PMID 35178414, 2022). "The TLR3 (rs3775291) SNP has been linked with a protective effect against other viral infections." (PMID 35967300, 2022). "TLR3 rs5743305 homozygosity may cause malfunction and make cells much more susceptible to viral infections." (PMID 36076988, 2022). "TLR3 pathway defects thus predispose humans to a narrow collection of viral infections." (PMID 34199501, 2021). "As TLR3 binds double-stranded RNAs (dsRNAs), its decreased level may increase susceptibility to viral infection in young foals." (PMID 33114637, 2020). "Limited evidence suggests that defective TLR3 signaling may also associate with a wider range of viral infections." (PMID 32936395, 2020). "This may suggest that differing mutations in TLR3 may predispose patients to different susceptibilities to viral infections or that TLR3 sensing is more critical for controlling HSV-1 than VZV." (PMID 32038653, 2020). "Currently, TLR3 research focuses on its antiviral activity, and both human and animal studies suggest that TLR3 may be a risk factor for viral infection." (PMID 29264743, 2018). "In addition, viral infections were associated with an increase in the percentage of samples with detectable TLR3 and IFN-λ1 mRNA." (PMID 30463560, 2018). "Based on our results, we hypothesize that TLR3 might be activated by a viral infection, which then induces miR-134 up-regulation and causes increased circulation of IL-18 in AOSD." (PMID 28646209, 2017). "Viral infection may predispose to bacterial pneumonia, activating toll-like receptor 3 (TLR3) on airway epithelium." (PMID 26739349, 2016). "Indeed, variations within the TLR3 locus (4q35) are associated with predisposition to viral infections and to systemic autoimmune diseases." (PMID 26318769, 2016). "Notably, TLR3, known to recognize dsRNA associated with viral infections, was also one of the up-regulated genes in the present study and is included in the gene ontology term “regulation of protein metabolic process”." (PMID 24755553, 2014). "Several studies have addressed TLR3’s role in virus infection using TLR3 deficient mice." (PMID 23435233, 2013). "Among these TLRs, TLR3 recognizes dsRNA, which is associated with viral infection." (PMID 23700487, 2013). "As functional deterioration of TLR3 can predispose individuals to increased susceptibility to viral infections, the detection of TLR3 polymorphisms may be informative for risk assessment in AERD susceptibility." (PMID 21837245, 2012). "Thus, long-term activation of TLR3 in vivo is thought to occur in the context of viral infection or necrosis associated with inflammation." (PMID 19486528, 2009). "Notably, children with inherited TLR3 deficiency are more susceptible to these viral infections." (PMID 40495154, 2025). "Therefore, it is believed that the mutation may passivate TLR3 signaling during the viral infection." (PMID 35462764, 2022).
viral infection (continued). "Thus, while TLR3 signaling variants confer an increased risk of certain viral infections, redundancy within the immune system for viral detection and other mitigating factors (e.g., age of exposure, variants within other immune related genes) likely restrict the clinical phenotype." (PMID 34199501, 2021). "Recently, it was considered that fucoidan could inhibit the release of cytokines from human primary bronchial epithelial cells via the Toll-like receptor 3 (TLR3); suggesting that it could relief bronchial inflammation caused by viral infection when applied locally." (PMID 32899754, 2020). "Moreover, some authors suggest that the activation of tlr3 could trigger the expression of genes encoding cytokines and proteins responsible for modulating the immune response against viral infections." (PMID 31611864, 2019). "The translocation of TLR3 from the endoplasmic reticulum to the cell surface is stimulated by the viral infection." (PMID 41614911, 2026). "TLR3, as an important pattern recognition receptor, plays a crucial role in immune system by monitoring viral infections and responding to pathological states." (PMID 40535567, 2025). "Previous studies on TLR3 have primarily concentrated on its role in recognizing viral infections, mediating inflammation, and activating immune cells." (PMID 40406122, 2025). "Toll-like receptor 3 (TLR3) is essential for innate immune responses to viral infections, including WNV." (PMID 41304172, 2025). "TLR3, localized primarily in endosomes, is specialized in recognizing double-stranded RNA (dsRNA) derived from viral infections." (PMID 40647457, 2025). "Among these receptors, TLR3 plays a crucial role in the innate immune response to viral infections, as it primarily recognizes dsRNA, which is produced during viral replication." (PMID 40909801, 2025). "The activation of these immune modulators facilitates the restriction and clearance of viral infections, reinforcing the irreplaceable role of TLR3 pathway in antiviral defense." (PMID 39988665, 2025). "Poly (I:C) is a synthetic double-stranded RNA that activates toll-like receptor 3 (TLR3), simulating viral infection." (PMID 40227198, 2025). "Given the role in viral infection surveillance, we investigated TLR3 (the receptor for poly I:C) in this study." (PMID 40842957, 2025). "It should be noted that TLR3 also plays an important role in antiviral defenses by triggering a potent immune response against dsRNAs produced during viral infection." (PMID 39990207, 2025). "Viral infections or endogenous nucleic acids engaging TLR3 can trigger local production of type I interferons, which in turn promote lymphocyte infiltration and apoptotic damage in salivary tissues." (PMID 41294018, 2025). "Viral infection activates the TLR-3 signaling pathway and the phosphorylation of IRF-3, which leads to its translocation to the nucleus." (PMID 40431442, 2025). "Subsequently, the activation of TLR3 in the viral infection was found to be most suitable by researchers." (PMID 40463364, 2025). "TLR3 is a critical receptor for recognizing dsRNA, which plays a central role in initiating immune responses to viral infections." (PMID 40359428, 2025). "It was demonstrated that Ze 339 reduces immune responses in human nasal epithelial cells triggered by diverse stimuli including poly I:C, a synthetic analogue of double-stranded RNA that simulates viral infections by activating Toll-like receptor 3 (TLR3)." (PMID 40558112, 2025). "First, while the study used poly(I:C) to mimic the TLR-3 pathway activated by single-stranded RNA (ssRNA) viruses, real viral infections involve several critical stages: attachment, penetration, uncoating, replication, assembly, and egress." (PMID 40431442, 2025). "Within‐group comparisons showed that NEV patients had significantly higher TLR3 expression in flat warts than in normal skin (p = 0.020), suggesting an adaptive response to viral infection." (PMID 41211638, 2025).
viral infection (continued). "While TLR3 has been well documented in the context of viral infections, its role in allergic diseases remains poorly understood." (PMID 40842957, 2025). "This suggests a potential mechanism for TLR3 induced pathogenesis, as CD8 + T-cell accumulation in airways has previously been associated with increase severity of lung injury in viral infections among infants." (PMID 39988665, 2025). "This coordinated activation facilitates the restriction and clearance of viral infections, underscoring the critical role of TLR3 signaling in antiviral immunity." (PMID 41304172, 2025). "Considering the critical role of TLR3 in triggering innate immune responses during viral infections, we detected the expression of TLR3 using IF and western blotting in TCE-caused kidney injury." (PMID 40842957, 2025). "PAR-1 has been shown to contribute to the innate immune response during viral infections by cooperating with toll-like receptor 3 (TLR3, which recognizes double-stranded (ds) RNA) to activate p38MAPK and IFN-β and CXCL10 expression)." (PMID 41009359, 2025). "TLR3 is a double-stranded RNA (dsRNA), which is found on the endosome membrane and plays a significant role in innate immune responses against viral infections." (PMID 39091390, 2024). "The NF-κB signaling and IFN response induced by TLR3 primarily serve as an innate defense mechanism against viral infections, providing a robust virus recognition system." (PMID 38694821, 2024). "Poly(I:C) binds to the toll-like receptor 3 (TLR3) in an organism, which results in the release of pro-inflammatory cytokines and initiates the inflammatory cascade in a fashion similar to a viral infection." (PMID 38534737, 2024). "TLR3 has been identified as the major MyD88-independent PRR stimulated in the type-1 IFN responses to many different viral infections due to its intracellular localization." (PMID 38172683, 2024). "We observed increased TLR-3 (toll-like receptor 3) expression in viral infection and KD in comparison with MIS-C and bacterial infection." (PMID 39300098, 2024). "As a dsRNA receptor, TLR3 is traditionally generated during most viral infections, whereas degraded bacteria, damaged tissues, and necrotic cells can induce TLR3 expression." (PMID 38374072, 2024). "TLR3 not only induces inflammation, but TLR3 activity also detects viral particles (double-stranded RNA) and provides protective immunity against viral infections." (PMID 39000127, 2024). "TLR3 is involved in the host response to viral infection, and has a possible role during Plasmodium infection through the initiation of complex circuits and signals of the immune response." (PMID 38172683, 2024). "The aim of this study is to characterize the response of MCs from PD patients to viral infections mimicked by TLR3 stimulation in terms of inflammatory/profibrotic response and subsequently analyze the role of HDAC1-3 inhibition." (PMID 38476167, 2024). "In the case of neurotropic viral infections, microglia recognize invading viral pathogen-associated molecular patterns (PAMPs) via PAMP recognition receptors (PRRs), such as Toll-like receptor 3 (TLR3) for viral double-stranded ribonucleic acid (dsRNA)." (PMID 38577490, 2024). "TLR3 is a sensor of viral infection and sterile tissue necrosis through the recognition of double-stranded RNAs." (PMID 38316991, 2024). "Viral infection was mimicked by administration of polyinosine: polycytidylic acid (poly I:C), a synthetic TLR3-agonist that mimics dsRNA viral nucleic acids." (PMID 38577490, 2024). "In this context, we studied the MC response to viral infection, focusing first on the role of TLR3, a sensor of virus-derived nucleic acids, in mediating changes in MC cell plasticity and the induction of an inflammatory response." (PMID 38476167, 2024). "TLR5 is commonly utilized in fish vaccine construction, while TLR3 plays a significant role in viral infections." (PMID 38782944, 2024).
viral infection (continued). "TLR3 recognizes viral infections and acts via the activation of interferon (IFN)/IFN‐stimulated genes (ISGs)." (PMID 38923445, 2024). "TLR3 agonist Poly(I:C), a synthetic analog of double-stranded RNA (dsRNA), impaired the viral infection by 45.5% at its highest concentration (p < 0.05)." (PMID 38791357, 2024). "The modulation of NF-κB and IRF-3 expression by OMT post-TLR3 silencing aligns with the broader understanding of TLR3′s involvement in viral infections and immune regulation." (PMID 38731436, 2024). "On the other hand, C/EBPα is crucial for the TLR3-mediated production of inflammatory cytokines and immune response to viral infections, and the silencing or knocking down C/EBPα has been shown to result in more severe disease." (PMID 39456732, 2024). "TLR3 activation owing to viral infection triggers type I IFN release from airway epithelial cells to restrict viral replication and activate adaptive immune cell." (PMID 38203397, 2023). "Poly (I:C) is a synthetic analog of double-stranded RNA that simulates a viral infection and induces the inflammatory response via TLR3 signaling and upregulates serine protease activities." (PMID 37256908, 2023). "This is surprising, as a correlation between the expression in the primary spot of viral infection and the clinical outcome would seem to be likely and TLR3 induction in lung is known to help lung recovery in COVID-19." (PMID 36631778, 2023). "TLR-3 is known to have contradictory properties in allergic diseases as well as in viral infections." (PMID 38140569, 2023). "Taken together, these findings imply that ST7 can prevent TLR3-induced inflammation and enhance the T-cell immune response during the early stage of viral infection." (PMID 36838243, 2023). "In this study, we have identified a key role of Usp25 in limiting cholesterol biosynthetic flux to trigger TLR3-dependent immune activation and restrict virus infection." (PMID 37683630, 2023). "Toll-like receptor 3 (TLR3) is a viral double-stranded RNA recognition receptor that, in viral infections, can exacerbate diseases by inducing tissue damage and facilitating viral dissemination." (PMID 37577440, 2023). "The most common virus infection-like model uses polyinosinic-polycytidylic acid (Poly IC), a synthetic dsRNA, which thus stimulates TLR3." (PMID 36673407, 2023). "For example, during viral infection, TBK1 can interact with virus-associated pattern recognition receptors (such as RIG-I and TLR3) and become activated." (PMID 37515271, 2023). "On the other hand, TRIM56 is known as an IFN-inducible gene and a positive regulator of TLR3 which can induce interferon and proinflammatory mediators produced during viral infection." (PMID 38051999, 2023). "Toll-like receptor 3 (TLR3), a pattern recognition receptor for double stranded RNAs, activates innate immune responses upon viral infections." (PMID 36761411, 2023). "Mainly four TLRs (TLR-3,4,7, and 8) broadly act as viral antigenic receptors and play a crucial role against viral infections whereas TLR-1,2,5,6,9–12 primarily work against bacterial infection." (PMID 36726141, 2023). "As a major mediator of cellular response to viral infection in mammals, Toll-like receptor 3 (TLR3) was proved to respond to double-stranded RNA (dsRNA)." (PMID 36670828, 2023). "This is a well-validated animal model produced by maternal exposure to a viral infection with Polyinosinic:polycytidylic acid (Poly I:C), a viral-mimicking agent which stimulates toll-like receptor 3 (TLR3) during pregnancy." (PMID 37107344, 2023). "Our results showed that TLR3 played a significant role in hybrid yellow catfish response to viral infection." (PMID 36670828, 2023). "Other glycoproteins involved in immune response to viral infection were also identified, including toll-like receptor 3 (TLR3)." (PMID 37709257, 2023).
viral infection (continued). "In detail, Toll-like receptor 3 (TLR3) is a receptor that can recognize and respond to viral infections, leading to activation of the innate immune system and intestinal inflammation." (PMID 36980164, 2023). "The present study raises the possibility that bacterial and viral infection through activation of TLR-3, TLR-4 and TLR-7/8, have the potential to alter fetal brain protection." (PMID 36721242, 2023). "Poly (I: C) mimics viral infections by signaling toll-like receptor 3 (TLR3), which induces the production of type I interferons (IFN-α and IFN-β)." (PMID 35055151, 2022). "In support of this, both prophylactic and post-exposure strategies involving specific innate immune stimulation, especially via TLR3, have been shown to be able to prevent or eliminate a range of viral infections." (PMID 35163772, 2022). "The rs3775290 polymorphism is located in the fourth exon, which affects the receptor–ligand interaction by changing the TLR3 extracellular domain and damaging the receptor function, thereby blunting TLR3 signaling during viral infection." (PMID 35462764, 2022). "During the last decade, much research has studied the canonical RLRs and RNA sensors RIG-I, MDA5, and TLR3, and has investigated their activation, expression, and mechanisms of regulation in response to agonists and virus infection." (PMID 35215908, 2022). "TLR3 is an important receptor that recognizes the dsRNA of viruses received from endosomes during viral infection." (PMID 35178414, 2022). "Signaling via TLR3, due to viral infection such as rhinovirus, exacerbates asthma and chronic rhinosinusitis." (PMID 35892679, 2022). "Some of these receptors, such as TLR3, a double-stranded RNA receptor, are reduced in eosinophils of allergic rhinitis patients, provide a link between viral infection and allergic exacerbation." (PMID 35185908, 2022). "In viral infection, TLR3 recognizes dsRNA and, through TRIF, transmits signals to activate the transcription factor IRF3." (PMID 35563088, 2022). "TLR3 is the endosomal receptor activated by viral dsRNA ligands to mediate transcriptional responses to viral infection." (PMID 35852150, 2022). "While TLR3 activation is important for an efficacious immune response towards viral infection, in the course of which dsRNA accumulates throughout viral replication, it has the potential to initiate undesirable effects." (PMID 36498932, 2022). "In the virus infection experiment of rainbow trout and rare minnow, TLR3 expression was significantly upregulated in immune tissues." (PMID 36232658, 2022). "Currently, the polyI:C model is widely used as a TLR3 activation model to mimic dsRNA virus infection." (PMID 34991643, 2022). "TLR3 is a key receptor for the recognition of dsRNA and the initiation of immune responses against viral infections." (PMID 36498932, 2022). "A previous study found that a ligand of TLR3 contributes to the viral-infection-induction of chemokine CCL5/RANTES secretion by airway epithelial cells to attract inflammatory cells." (PMID 35563088, 2022). "This study first identified the substrates and inhibitory function of RNF170 in TLR3-mediated innate immune responses, thereby enhancing viral infection and pathogenesis and providing a potential target for controlling TLR3-related inflammatory diseases." (PMID 36042206, 2022). "To further investigate this potential mechanism, we treated alveolar type 2 cells with TGFβ in the absence or presence of the synthetic TLR3 agonist, polyinosinic:polycytidylic acid (poly I:C), to mimic viral infection." (PMID 35977489, 2022). "TLR3 is a nucleotide-sensing TLR that is activated by double-stranded RNA as a sign of viral infection." (PMID 37529092, 2022). "In the MIA model, pregnant female mice are exposed to a simulated viral infection by injection with the toll-like receptor 3 (TLR3) agonist poly(IC)." (PMID 33735311, 2021).